PRTG (protogenin)
Description:
May play a role in anteroposterior axis elongation.
Synonyms: FLJ25756; IGDCC5
Tractability: Antibody: UniProt predicts a signal peptide or a membrane-spanning region; its Gene Ontology location is reachable by antibodies, with medium confidence; the Human Protein Atlas places it where antibodies can reach.
Gene: Protein-coding gene on chromosome 15 (55,611,544 to 55,743,152, reverse strand). Ensembl gene ENSG00000166450.
Subcellular location: Membrane
Subcellular location (Human Protein Atlas): Cytosol; Plasma membrane; Vesicles
Gene Ontology:
Molecular function: protein binding; identical protein binding; signaling receptor activity
Biological process: cell-cell adhesion; negative regulation of neurogenesis
Cellular component: extracellular region; membrane; plasma membrane
Genetic constraint (gnomAD): Loss-of-function variants: 47 observed, 87.46 expected, observed/expected ratio (o/e) 0.54, 90% interval 0.42 to 0.69. The upper end of that interval is the gene's LOEUF score, 0.69, which puts it in group 2 of 6, group 1 being the genes least tolerant of losing a copy. Missense variants: 1,106 observed, 1,091.8 expected, observed/expected ratio (o/e) 1.01, 90% interval 0.96 to 1.07. Synonymous variants: 437 observed, 396.11 expected, observed/expected ratio (o/e) 1.1, 90% interval 1.02 to 1.19.
Homologues: Orthologues: chimpanzee PRTG (99% identical), macaque PRTG (98% identical), dog PRTG (96% identical), pig PRTG (94% identical), mouse Prtg (90% identical), rat Prtg (90% identical), guinea pig PRTG (83% identical), tropical clawed frog prtg (70% identical), zebrafish prtga (6% identical). Paralogues in human: IGDCC4 (35% identical), IGDCC3 (25% identical), DCC (22% identical), ROBO1 (21% identical), NEO1 (21% identical), ROBO2 (21% identical), SDK1 (20% identical), CDON (20% identical), SDK2 (20% identical), ROBO3 (19% identical), BOC (18% identical), CNTN5 (17% identical), and 24 more.
Diseases named in the same sentence as PRTG in open-access papers:
PRTG is named in the same sentence as 11 diseases in open-access papers, as found by Europe PMC text mining. Sharing a sentence is not in itself a finding about the gene and the disease. The quoted sentences say what the papers report.
gastric cancer (6 papers, 2021 to 2025). A primary or metastatic malignant neoplasm involving the stomach. "In this study, by comparing mRNA expression profile associated with both gastric cancer progression and H. pylori infection, we have identified a novel oncogenic role of H. pylori-upregulated PRTG in gastric cancer." (PMID 33542225, 2021). "In addition, ZEB1 positively associated PRTG expression and increased in gastric cancer tissues, as well as predicted poor prognosis of gastric cancer patients." (PMID 33542225, 2021). "In Helicobacter pylori infection, activation of the cGMP/PKG signaling pathway leads to the occurrence and development of gastric cancer, while blocking the PRTG/cGMP/PKG axis holds potential for gastric cancer treatment." (PMID 38205153, 2024). "PRTG expression was previously reported to be upregulated in Helicobacter pylori-infected gastric cancer tissues." (PMID 36292752, 2022). "In the present study, overexpression of PRTG enhances survival, metastatic and chemoresistant potential in gastric cancer cells both in vitro and in vivo." (PMID 33542225, 2021). "Strikingly, we found that PRTG, a cell adhesion related protein, was significantly upregulated in gastric cancer tissues and H. pylori-infected tissues." (PMID 33542225, 2021). "Next, we further confirmed that overexpression of ZEB1 significantly enhanced the expression of PRTG in gastric cancer cells." (PMID 33542225, 2021). "In this study, we identified Protogenin (PRTG) was upregulated in both gastric cancer tissues and H. pylori-infected tissues by analyzing dysregulated genes in TCGA and GEO databases." (PMID 33542225, 2021). "In our current study, we identified Protogenin (PRTG) was upregulated in both gastric cancer tissues and H. pylori-infected tissues by analyzing dysregulated genes in TCGA and GEO databases." (PMID 33542225, 2021). "Overall, our results suggest that ZEB1-mediated transcription of PRTG is critical to the activation of cGMP/PKG signaling pathway induced by H. pylori infection in gastric cancer." (PMID 33542225, 2021). "Consistent with bioinformatics analysis results, the expression levels of PRTG were significantly elevated in gastric cancer tissues and gastric cancer cell lines." (PMID 33542225, 2021). "Taken together, our findings suggested that H. pylori infection depends on ZEB1 to induce PRTG upregulation, and which leading to the development and progression of gastric cancer through activating cGMP/PKG signaling pathway." (PMID 33542225, 2021). "We validated the oncogenic roles of PRTG in gastric cancer by activating the downstream cGMP-PKG signaling pathway." (PMID 33542225, 2021). "Then, we further manipulated and evaluated the oncogenic role of PRTG in MGC-803 cells, which has the lowest PRTG expression within different gastric cancer cell lines." (PMID 33542225, 2021). "In clinical setting, PRTG expression was upregulated in H. pylori-infected gastric cancer tissues." (PMID 33542225, 2021). "Indeed, our data demonstrate that the cGMP/PKG signaling-associated proteins, including sGC, PKG1/2 and pVASP were significantly upregulated by PRTG in gastric cancer cells." (PMID 33542225, 2021). "Indeed, H. pylori infection and ZEB1 overexpression activated cGMP/PKG pathway in gastric cancer cells, and which can be blocked by the PRTG silencing." (PMID 33542225, 2021). "In addition, the addition of sGC inhibitor NS-2028 and PKG inhibitor KT5823 significantly blocked the increase of cGMP levels and pVASP levels in gastric cancer cells induced by PRTG overexpression." (PMID 33542225, 2021). "Furthermore, KT5823 also blocked the chemoresistant effects of PRTG in gastric cancer cells in response to CDDP and paclitaxel, as reflected by enhanced apoptosis and pH2AX foci formation." (PMID 33542225, 2021). "Furthermore, patients with higher PRTG expression presented with worse overall survival in gastric cancer patients from the local hospital, GEO dataset GSE62254 and TCGA database." (PMID 33542225, 2021).
gastric cancer (continued). "Thus, blocking PRTG activation through compounds specifically target to cGMP-PKG signaling pathway could provide a novel therapeutic approach to treat gastric cancer." (PMID 33542225, 2021). "Importantly, upregulated PRTG predicted poor prognosis of gastric cancer patients and integrative analysis revealed that PRTG served as an oncogenic protein in gastric cancer and was required for H. pylori-mediated tumorigenic activities in in vitro cellular and in vivo tumor-bearing mouse models." (PMID 33542225, 2021). "Cellular studies further confirmed that PRTG depended on activating cGMP/PKG axis to promote proliferation, metastasis, and chemoresistance of gastric cancer cells." (PMID 33542225, 2021). "Taken together, these data demonstrate a requirement for cGMP/PKG pathway activation in PRTG-mediated oncogenic activities and supports PKG inhibition as a viable therapeutic strategy against gastric cancer." (PMID 33542225, 2021). "Blocking PRTG/cGMP/PKG axis, therefore, presents a promising novel therapeutic strategy for gastric cancer." (PMID 33542225, 2021). "In gastric cancer cells, PKG inhibitor KT5823 treatment significantly reversed the promotive effects of PRTG on proliferation, invasion and migration." (PMID 33542225, 2021). "PRTG activates the cGMP/PKG signaling pathway downstream of gastric cancer cells in response to the induction of the epithelial-mesenchymal transition (EMT) transcription factor ZEB1, which has an important role in the progression of gastric cancer." (PMID 36292752, 2022). "Although we demonstrate that PRTG plays important oncogenic role in H. pylori-associated gastric cancer, but a detailed understanding of how PRTG contributes to gastric cancer progression is still lacking." (PMID 33542225, 2021). "Next, PRTG expression was manipulated in AGS cells, which had the highest level of PRTG expression and is known as a low-grade malignant gastric tumor cell line, to identify its biological functions in gastric cancer." (PMID 33542225, 2021). "As predicted, PRTG overexpression led to a significantly elevated mRNA expression of GUCY1A2, GUCY1A3 and GUCY1B3 (mRNA components of sGC enzyme), as well as sGC protein expression in gastric cancer cells." (PMID 33542225, 2021). "Owing to the lack of suitable blockers target to ZEB1/PRTG axis, the development of more specific and pharmacologically tractable antagonists that block PKG1α activity could provide novel approaches to improve gastric cancer outcomes." (PMID 33542225, 2021). "Furthermore, PRTG overexpression also inhibited apoptosis induced by cisplatin (CDDP) and paclitaxel, which are chemotherapeutic drugs commonly used systemically in gastric cancer treatment, and PRTG silencing significantly enhanced chemosensitivity of gastric cancer cells." (PMID 33542225, 2021). "To explore whether H. pylori infection depended on ZEB1 to induce PRTG expression, we firstly detected the expression of ZEB1 in H. pylori-infected and non-infected gastric cancer tissues." (PMID 33542225, 2021).
breast carcinoma (1 paper, 2025). "Using this capability, we detected and validated three genes—PCDHA10, PRICKLE2, and PRTG—demonstrating their inhibiting effects on cancer cell growth and migration in breast cancer cell lines." (PMID 40581983, 2025). "Using cfMethylPre, we identified and validated three novel genes—PCDHA10, PRICKLE2, and PRTG—that exhibit inhibitory effects on breast cancer cell proliferation and migration, highlighting its potential in precision oncology." (PMID 40581983, 2025). "Furthermore, its interpretability enables the identification of critical cancer-associated genes, with experimental validation uncovering three novel genes—PCDHA10, PRICKLE2, and PRTG—that exhibit inhibitory effects on breast cancer cell proliferation and migration." (PMID 40581983, 2025). "Through model interpretation and biological experimental validation, we identified three novel breast cancer genes—PCDHA10, PRICKLE2, and PRTG—demonstrating their inhibitory effects on cell proliferation and migration in breast cancer cell lines." (PMID 40581983, 2025).
colorectal cancer (1 paper, 2013). A primary or metastatic malignant neoplasm that affects the colon or rectum. "Protogenin (PRTG) belongs to the immunoglobulin superfamily and is most closely related to the deleted in colorectal cancer (DCC)-Neogenin subclass, which, in addition to DCC and Neogenin, includes Punc and Nope." (PMID 24007463, 2013).
diabetes (1 paper, 2019). "Several other genes displaying inverted correlations have previously been linked to diabetes (7/18), either by functional studies (TRIB1, glucose metabolism; NFKBIA, insulin resistance pathway) or as candidate disease genes in GWAS or gene expression studies (TMPPE, PRTG, and ZNF319)." (PMID 31159854, 2019).
epilepsy (1 paper, 2019). A brain disorder characterized by episodes of abnormally increased neuronal discharge resulting in transient episodes of sensory or motor neurological dysfunction, or psychic dysfunction. "PRTG, TNC and MACF1 are candidate recessive epilepsy genes and our work highlights that inheritance of CH variants should not be excluded from gene discovery or diagnostic analyses of patients with epilepsy." (PMID 31190668, 2019). "Given both the enrichment in Epi4k probands for CH variants in these genes as well as their known involvement in neuronal processes, we suggest that PRTG, TNC and MACF1 are candidate recessive epilepsy genes." (PMID 31190668, 2019). "However, PRTG, TNC and MACF1 are potential novel recessive epilepsy genes and our results highlight that compound heterozygous variants should be considered in sporadic epilepsy." (PMID 31190668, 2019).
osteoarthritis (1 paper, 2013). A noninflammatory degenerative joint disease occurring chiefly in older persons, characterized by degeneration of the articular cartilage, hypertrophy of bone at the margins and changes in the synovial membrane. "Studies have shown the roles of miR-9 and its validated target, protogenin (PRTG) in the differentiation of chondroblasts to chondrocyte and in the pathogenesis of osteoarthritis (OA)." (PMID 24007463, 2013).
cancer (2 papers, 2021 to 2025). A tumor composed of atypical neoplastic, often pleomorphic cells that invade other tissues. "Therefore, our study firstly reveals the possibility that PRTG acts as an oncogenic protein in cancer cells." (PMID 33542225, 2021).
PRTG also shares sentences with these, for which no sentence is quoted: Brain atrophy (1 paper); gastric tumor (1); infection (1); tumor (1).